CD4 (CD4 molecule)
Diseases named in the same sentence as CD4 in open-access papers (continued):
Sharing a sentence is not in itself a finding about the gene and the disease.
infection (continued). "Upon resolution of primary Leishmania infection, patients exhibit a long-lasting, CD4+ T cell-dependent concomitant immunity to reinfection, but 102 - 104 parasites remain detectable at the site of primary infection and in the draining lymph nodes." (PMID 34093571, 2021). "With CB4 infection, effector T cells (CD4+ and CD8+) are significantly reduced in MDA5+/- mice PLNs and spleen." (PMID 34804036, 2021). "CXCR3 is associated with the recruitment of both CD4+ and CD8+ T cells to the site of infection, IFN-γ secretion from the T cells, and the resultant activation of inflammatory monocytes." (PMID 34835465, 2021). "We further show that proviral turnover during untreated infection correlates with both viral setpoint and rate of CD4+ T-cell decline during this period." (PMID 34489909, 2021). "This enabled the simultaneous identification of antigens marking preferentially infected cells (by comparing PRE and UI memory CD4+ T cells) and of antigens remodeled by infection (by comparing the PRE and infected cells)." (PMID 33910003, 2021). "Infection with the human immunodeficiency virus (HIV) is characterized by progressive depletion of CD4+ lymphocytes cells as a result of chronic immune activation." (PMID 33643320, 2021). "Around the time the worm is expelled (day 14 after infection), CD4+ T helper cells accumulate in the colonic epithelium." (PMID 34451389, 2021). "IL-2-secreting CD4 T cells were only observable at later time points of infection, and very low frequencies of IL-10-secreting CD4 T cells were detected in this organ." (PMID 34959486, 2021). "Different subtypes of CD4+ T cells are characterized by their cytokine secretion profile and are distinctively involved in protection against infection and further regulation of T cells." (PMID 34440709, 2021). "In the natural course of infection, CD4+ T cells appear in the blood simultaneously with CD8+ T cells between 7 to 10 weeks after infection and before symptoms develop." (PMID 34066322, 2021). "Women with lower CD4 cell counts were more likely to have persistent hrHPV infection, confirming the effect of immune status on HPV persistence." (PMID 33608036, 2021). "Women with higher CD4 cell counts were less likely to have a persistent hrHPV infection as well as multiple hrHPV infections most likely due to better immune responses resulting from improving HIV care and management." (PMID 33608036, 2021). "Mice previously immunized and infected (EV + P. brasiliensis) displayed increased counts of activated CD4-positive T cells in the BAL upon infection." (PMID 34359982, 2021). "Numbers of splenic cytotoxic CD8αα+ and CD8αβ+ T cells as well helper CD4+ T cells were similar between uninfected and SE-infected chickens during the course of infection." (PMID 34404469, 2021). "We have previously shown that B cell-mediated trans infection of CD4+ T cells is inhibited by blocking of DC-SIGN." (PMID 33688006, 2021). "In contrast, the number of IFNγ-producing NP396–404-specific CD8 T cells were similarly deleted in Rb-treated and PBS-treated CD4−/− mice following LCMV-Cl13 infection." (PMID 34206262, 2021). "On the other hand, patients with severe infection had lower CD4+, CD19+ and CD146+ levels compared with healthy individuals." (PMID 34440265, 2021). "T-REX identified rhinovirus-specific CD4+ T cells based on phenotypically homogeneous cells expanding by ≥95% following infection." (PMID 34350827, 2021). "One explanation for this is the assumption that all CD4 counts at seroconversion are high (>500 cells per μL), ignoring the short acute infection period when CD4 counts can rapidly decrease." (PMID 34118196, 2021). "Additionally, several authors have published reports describing that during the formation of nurse cells, several cell types are recruited, among them eosinophils and CD4 cells, which could control the inflammation caused by the parasite 40 days after infection." (PMID 34832538, 2021).
infection (continued). "To study the effect of the cellular environment on HIV-1 fate at high resolution, we analyzed the transcriptome of primary CD4+ T cells after infection of these cells with HI.fate viruses." (PMID 34469717, 2021). "After the second dose of vaccination, convalescent individuals harbored more long-lived (CD127+ CD57-) spike-specific CD4+ T cells than infection-naïve individuals." (PMID 34636722, 2021). "In Giardia, there is little research focused on characterizing the cellular response, however, it is known that CD4+ T lymphocytes play an important role in infection." (PMID 34778111, 2021). "Contrary, all DC subtypes were able to present antigens to virus-specific CD4+ T cells at day five after infection in the axillary and brachial lymph nodes." (PMID 34895058, 2021). "TRBJ2-7 accounted for the largest number of TRBJ in the total T cells and CD8 cells for each sample, except for TRBJ1-1 in CD4 cells at 3 W after infection." (PMID 33959105, 2021). "So, in acute self-limiting infection, a strong, multi-specific Th1 CD4+ T cell response is elicited that has a crucial role in HBV control." (PMID 34066322, 2021). "Nonetheless, the main findings we made with the CD4+ T cells – that they recognize variants equivalently, and that the phenotypes of the responding cells differ by prior SARS-CoV-2 natural infection status – were recapitulated among CD8+ T cells." (PMID 34636722, 2021). "Sur le plan infectieux: le bilan de l'infection par le VIH a retrouvé un taux de CD4 à 30/mm3 et une charge virale à 1573, 3 copies soit 4, 72 log, la classant au stade C de l'OMS." (PMID 35686173, 2021). "Core body and surface body temperature were also checked at different time intervals post-infection and after CD4+ T cell transfer." (PMID 34899731, 2021). "This latent infection occurs within long-lived cells, including resting CD4+ T cells, follicular dendritic cells, and hematopoietic stem cells, and can be established at a very early stage of infection." (PMID 33504604, 2021). "We compared T-cell immune responses over time after infection or vaccination using ELISpot, and memory CD4+ T-cell responses three months after infection/vaccination using activation-induced marker flow cytometric assays." (PMID 34960185, 2021). "This corresponds to human data depicting a cytolytic effector function of EBV specific CD4+ T cells during infection." (PMID 33833760, 2021). "To measure this ability, we purified CD4+ T cells from the lungs of B6 or pMT-10 mice at day 30 after infection and adoptively transferred them intravenously into recipient RAG–/– mice infected for 15 days." (PMID 34554927, 2021). "By day 35, 4 weeks after infection, all remaining CD4+ cells were CD69+ TRM cells in these resting lungs, and they localized exclusively around the conducting airways." (PMID 34611166, 2021). "The induced effector CD4+ T-cell response is also modulated by pneumococcal-specific regulatory T cells (Tregs) to prevent excessive tissue damage and subsequent severe infection due to compromised tissue integrity and barriers." (PMID 35822055, 2021). "Active viral transcription (spliced viral RNA) was present in CSF CD4+ T cells as early as four weeks post-SHIV infection, and among all acute HIV-1 specimens (N = 6; Fiebig III/IV)." (PMID 34874976, 2021). "A key role in maintaining the infection is played by CD4+ T cells through the constant production of interleukin-12 (IL-12), which is responsible for keeping the differentiation of Th1 effector cells ongoing." (PMID 34946062, 2021). "T. cruzi-infected children, who are presumed to have shorter-term infections compared with adults, showed a higher proportion of polyfunctional CD4+ T cells responsive to T. cruzi antigens in their circulation relative to chronic infected adults." (PMID 34061845, 2021).
infection (continued). "Given that the infection promoted the generation of a high frequency of IFN-γ-producing CD4+ and CD8+ T effectors in AT, the contribution of IFN-γ was assessed by infecting Ifng-/- mice." (PMID 34525131, 2021). "In mouse models, antibody depletion of CD4+ T cells during the chronic phase of infection also results in reactivation." (PMID 34943793, 2021). "These HIV-1 reservoirs mainly comprise long-lived resting memory CD4+ T cells and are established early after infection." (PMID 34781942, 2021). "Rapid progression was defined as two consecutive CD4+ T cell counts < 350/μL within 3–24 months post-infection." (PMID 34367176, 2021). "A possible explanation for these observations is that interactions between macrophages and infected CD4+ T cells are needed to achieve high levels of macrophage infection." (PMID 33594125, 2021). "CD27+CD127+CD4+ T cells have been previously found in other infection settings and appear to have features of stem-like central memory T (TSCM) cells with self-renewal capacity." (PMID 34128836, 2021). "IL-21 produced by CD4+ T cells during LCMV Cl 13 infection and signaling through the IL-21 receptor is crucial for maintaining antiviral CD8+ T cell responses and ensuring clearance of infection." (PMID 34696381, 2021). "A significant increase in the proportion of cytokine-producing CD4+ Tem (CD44+CD62L−) in spleens after the protein stimulation was observed in all vaccinated groups of animals compared to infection control." (PMID 34835204, 2021). "An analysis performed in the lymph node draining the site of infection revealed an increase of the parasite-specific IFN-Υ production by CD4+ and CD8+ T cells and a decrease in the secretion of IL-10 against leishmanial antigens." (PMID 33673117, 2021). "As expected, CD4+ T cells robustly upregulated type 2 cytokines IL-4, IL-5 and IL-13 by day 7 post-infection." (PMID 34237106, 2021). "Taken together, these results indicate that pEVs secreted by cells exposed to HIV harbour factors which promote the infection of healthy CD4+ T cells." (PMID 34249000, 2021). "Collectively, memory CD4+ T cells appear to be the major targets for primary infection, and viral reservoirs are equally distributed in systemic and lymphoid compartments in acutely SIV-infected macaques." (PMID 34960667, 2021). "Patients who experienced an infection during the study period had significant higher frequencies of EM CD4+ and TEMRA CD8+ cells." (PMID 34749733, 2021). "The simulations also indicate that the CD4+ T cell population in the lungs should rise more slowly than that in the lymphoid tissues: a third of the peak after four days of infection." (PMID 34343169, 2021). "Trends in mLN CD8+ and CD4+ T-cell frequency indicate potential alterations in these cell populations following both primary infection and vaccination and challenge." (PMID 33741986, 2021). "Protecting CD4+ T cells against infection with CCR5-tropic HIV strains is possible via knockout of the HIV co-receptor CCR5." (PMID 34112993, 2021). "Their estimates of latently infected CD4 T cells exceeded the estimates of infection with replication-competent proviruses, providing early evidence of the largely defective proviral populations that accumulate during long-term ART." (PMID 34960781, 2021). "Taken together with the capture/phagocytosis data, we assert that the improved infection of MDMs is likely a consequence of their engulfment of infected CD4+ T cells." (PMID 34425695, 2021). "In Th1-skewed infections, CD4+ T cells differentiate into Tfh cells, Th1 cells, and memory cell populations in parallel." (PMID 32999454, 2021). "Focusing on the initial stage of i.vag. infection (day 6 post infection), we interrogated the effect of miR-135a on CD4+ T cell function which has been implicated in early stages of genital chlamydial infection." (PMID 33928045, 2021).
infection (continued). "It codes for a receptor protein that is vital for antigen-presenting cells, for example, in presentation of the hepatitis B virus to CD4+ helper T cells following infection." (PMID 34573352, 2021). "The CD8+ population appears to be decreased while the CD4+ population appears to be increased following infection in vaccinated, challenged animals compared to that of unvaccinated, challenged animals." (PMID 33741986, 2021). "We found that TKO mice compared to WT mice had significantly increased numbers of naïve CD4+ T cells as well as comparable numbers of central memory T cells (Tcm) and Tem cells throughout the infection (G’’, G’’’)." (PMID 33968021, 2021). "CD4+ Tregs contribute to homeostasis of the immune system, controlling infection by respiratory viruses and avoiding secondary bacterial infection." (PMID 33497364, 2021). "Treatment of mice with anti-CD4 by intranasal (i.n.)and intraperitoneal (i.p.)administration of the antibodies from day 7 of infection significantly reduced the numbers of CD4 T cells in the nasal tissue during infection with B. pertussis." (PMID 33976385, 2021). "Over 20% of all CD4 TRM cells in the nasal tissue on day 28 of infection were IL-17-secreting B. pertussis-specific TRM cells." (PMID 33976385, 2021). "The concentration of maraviroc used was previously determined to significantly inhibit direct, cis infection of total CD4+ T cells, where expression of CCR5 is significantly higher than the very low or negative expression of CCR5 in TN alone." (PMID 33688006, 2021). "Expansion of CD11a+2W1S+CD4+ T cells also occurred to a lesser extent in the lung-draining mediastinal lymph nodes (mdLN) following one infection, and was similarly proportional to antigen load following three Hulk inoculations." (PMID 34237106, 2021). "In fact, best correlates of protection for infections with other intracellular pathogens have been multifunctional CD4+ T cells, capable of producing IFN-γ, TNF-α and IL-2 simultaneously." (PMID 34451970, 2021). "Treg cells also dulls the CD4 and CD8 functions, which increases one’s susceptibility to infection and cancers." (PMID 34072224, 2021). "These combined results suggest the essential requirements for CD4+ T cells and IFNγ in protective immunity against challenge infection with B. microti." (PMID 34414129, 2021). "In comparison to NT fSFs, HAS2KO fSFs supported trans-infection more efficiently and better conditioned CD4+ T cells for HIV infection." (PMID 33976386, 2021). "Surprisingly, in both donors, we also identified a group of predominantly CD4+ clonotypes that expanded from day 15 to day 37 after the infection." (PMID 33399535, 2021). "Six individuals lost LTNP status 14.5 (IQR: 12.5–17.5) years after infection (DG), and the CD4+ T cell count decreased to 237 (IQR: 213–320) cells/μL at the latest visit." (PMID 34082709, 2021). "Binding to DC-SIGN prevents HIV from entry in DCs through a pathway that supports productive infection: the viral envelope fusion mediated by CD4/coreceptor CCR5 or CD4/coreceptor CXCR4 interactions." (PMID 34421929, 2021). "We found that direct infection of resting CD4+ T cells by HIV was markedly increased in the presence of IP-10, which promotes actin dynamics necessary for viral entry and nuclear migration." (PMID 34447368, 2021). "Infection of different cell types was quantified using multiparameter flow cytometry as previously detailed, and CD11c+ DCs and CD4+ T cells were productively infected as evidenced by an infection block under AZT treatment." (PMID 33637808, 2021). "(E) Spike-specific CD4+ T cells are phenotypically distinct between the infection-naïve and convalescent individuals." (PMID 34636722, 2021). "The confirmation of transcriptomic responses to infection in memory as well as total primary CD4+ T cells and with multiple X4- and R5-tropic viral strains further validated the generality of our findings." (PMID 34154423, 2021).
infection (continued). "We developed a combination assay that uses autologous CD8 T cells from HIV controllers to suppress a heterologous infection of autologous CD4 T cells by virus that has been previously allowed to form immune complexes with bNAbs." (PMID 34394110, 2021). "wP primed BP specific CD4+ T cell immunity is Th1/Th17 biased which mimics cellular immunity profile after natural infection." (PMID 35222350, 2021). "Early in the infection course, cytokine production is compromised, serum levels in infected patients correlate with CD4+ T cell count." (PMID 34784398, 2021). "The application of this methodology to lymphoid tissues offers a means to interrogate multiple relevant immune cell targets simultaneously at increased resolution in a reproducible manner to guide CD4 T-cell studies in infection and vaccination." (PMID 34177929, 2021). "We profiled lung CD4+ T cells 8 hours after infection, when Spn-specific TRM cells already bolster neutrophil recruitment." (PMID 34611166, 2021). "PBMC and LNMC CD4+ T cell infection levels were similar to that of CSF at week 4 PI (0.05%-1.6% and 0.03%-1.5%, respectively) and week 12 PI (0.02%-6.6% and 0.1%-0.2%, respectively)." (PMID 34874976, 2021). "In this study, GNAstV infection increased levels of CD4 and decreased levels of CD8 at the early stages of infection." (PMID 34207913, 2021). "Depletion of CD4+ T cells results in disorganized granuloma structure, reactivation and dissemination of infection, and eventually death of the animal." (PMID 34943793, 2021). "Human T cell leukemia virus (HTLV) demonstrate productive infection and expansion of virus specific CD4 + T cells." (PMID 34090462, 2021). "The percentages and total numbers of CD4+CD25+Foxp3+ T cells diminished within three weeks of infection in animals treated with anti-IL-2 mAb." (PMID 34869064, 2021). "Compared with 4-week-old mice, the percentage of CD4+T-bet+IFN-γ+ Th1 cells as well as IFN-γ production were significantly increased on day 5 p.i. in the 8-week-old mice after P. yoelii 17XNL infection." (PMID 33430765, 2021). "In humans and experimental mouse infection models, CD4+ helper T cells that have differentiated into type 2 (Th2) effectors serve important roles in worm clearance and are considered essential for specific, long-lasting immunity." (PMID 34237106, 2021). "We previously reported that LCs are the early cellular targets of HIV-1 upon its mucosal entry in the inner foreskin, and subsequently transfer infectious virus to CD4+ T-cells in a process termed trans-infection." (PMID 34956215, 2021). "Peripheral immune response dynamics were similar after the infection with both isolates, with a significant increase in the percentage of CD4+ T cells at 6 and 9 dpi in PBMC, coincident with the higher levels of IFN-γ and IL-4 release." (PMID 34239816, 2021). "The frequency of Th1 cells in the CD4+ T cell population was also increased in brains upon infection." (PMID 34025654, 2021). "One study showed that tick infection can generate IL-3+ CD4+ TRMs distant from the primary tick infection site, potentially leading to efficient control at re-infection." (PMID 34445713, 2021). "Despite current strategies to treat HIV infection and its complications, Pneumocystis (PC) pneumonia remains a common clinical problem thus there is a need to develop CD4+ T cell–independent therapeutic strategies to prevent this infection." (PMID 34975811, 2021). "One of the major cell types identified to produce IL-10 during LCMV Cl 13 infection is virus-specific Th1 CD4+ T cells." (PMID 34696381, 2021). "Then, the CD4+ T-cell count at diagnosis was applied against the modelled slopes to estimate infection length." (PMID 34414881, 2021). "Classiquement la HIVAN constitue une complication tardive de l'infection survenant chez un patient VIH mal contrôlé dont le taux de CD4 est bas, la charge virale élevée et qui a des antécédents d'infections opportunistes." (PMID 35686173, 2021).